CCR2 (C-C motif chemokine receptor 2)
Diseases named in the same sentence as CCR2 in open-access papers (continued):
Sharing a sentence is not in itself a finding about the gene and the disease.
tumor (continued). "By binding to its receptor CCR2, CCL2 mainly promotes the recruitment of monocytes and pro-macrophages to the tumor microenvironment." (PMID 40109347, 2025). "Specifically, lactate enhances the production of C-C motif chemokine ligand 2 (CCL2) and C-C motif chemokine ligand 7 (CCL7) by tumor cells in CRC, thereby driving the recruitment of CCR2+ polymorphonuclear MDSCs (PMN-MDSCs)." (PMID 41152975, 2025). "Both CCL2 and CCL7 serve as ligands for the chemokine receptor CCR2 17, which was found to be overexpressed in TRPC tumor infiltrates." (PMID 40661379, 2025). "In particular, CCR2 contributed to decreased α-SMA fibroblast accumulation and tumor angiogenesis, MET contributed to FSP1+ fibroblast and both CCR2 and MET contributed to M2 macrophages." (PMID 40736024, 2025). "Key chemokine receptors, such as CCR2, CCR6, CCL20 and CXCR4, have been identified as pivotal contributors to Treg recruitment at tumor sites." (PMID 41445742, 2025). "Next, active TAFs are fed back to tumor cells through the secretion of CCL2 and its receptor CCR2 on the membrane of LGALS3+ cells." (PMID 40600063, 2025). "One, three and five days after the removal of the primary tumor, ATs with CD115+ cells from both BL6 and Ccr2-/- mice restored metastasis in Ccr1-/- mice to the same levels as observed in BL6 mice." (PMID 39566333, 2025). "CD36 displayed strong positive correlations with immune receptors such as CCR1, CCR2, CCR4, CXCR1, and CXCR2, indicating its potential role in amplifying chemokine-receptor interactions and shaping immune cell trafficking within the tumor microenvironment." (PMID 41550652, 2025). "In our study, postoperative CCR2–4, PCI > 20, and tumor grade 3–4 were identified as independent factors affecting patient prognosis and OS." (PMID 41341392, 2025). "Chitosan-DNA nanoparticles/siRNA targeting CCR2 (CNP/siCCR2) nanoparticles inhibit TAM recruitment, reduce tumor immunosuppression, and enhance chemotherapy efficacy in BC models." (PMID 40092996, 2025). "A high concentration of CCR2+ monocytes, which is a characteristic of the classical monocyte subset, within the TME is correlated with T cell suppression and promotion of tumor growth in several cancer models." (PMID 41440002, 2025). "Meanwhile, simultaneous blockade of CCR2 and CXCR2 can synergistically inhibit tumor and enhance chemotherapy response." (PMID 41341593, 2025). "The CCL2/CCR2 axis, which regulates monocyte recruitment and differentiation into TAMs, has been effectively targeted to disrupt TAM function and enhance tumor sensitivity to immunotherapy." (PMID 40098971, 2025). "Some studies have suggested redundant roles for CCL2 and CCL4 so we expected that our CCR2 and CCR5 armored CAR-T cells would be equivalent in terms of in vitro and in vivo tumor-directed homing and efficacy." (PMID 41424784, 2025). "Tumor angiogenesis plays a crucial role in tumor growth, maintenance and metastasis, and CCL2/CCR2 axis plays a key role in the angiogenesis of OSCC." (PMID 41445742, 2025). "As mentioned in the previous section, targeting the CCR2/CCL2 signalling axis as well as VEGFR2 can reduce macrophage infiltration and suppress tumour growth in murine models." (PMID 40385641, 2025). "CD11b is a general myeloid marker, while CCR2, CSF1R, and CD206 are typically expressed in inflammatory monocytes and macrophages, with CD206 serving as a canonical marker of tumor-promoting M2-polarized macrophages." (PMID 40867322, 2025). "The tumor immune microenvironment was remodeled by PPARG via recruiting and promoting the M2 polarization of macrophages through the CCL2/CCR2 signaling axis." (PMID 40183093, 2025). "Gene knockout experiments further demonstrated that CCL2 inhibition reduces BMDM recruitment, delays tumor progression, and prolongs survival in murine models, suggesting that the CCL2/CCR2 axis is a potential therapeutic target for GBM immunotherapy." (PMID 41002423, 2025).
tumor (continued). "Subsequent targeting has proven critical; a neoadjuvant CCR2 inhibitor (PF‐04136309) depletes TAMs, inhibiting GOLM1‐mediated colorectal cancer (CRC) metastasis in residual tumor cells." (PMID 40904700, 2025). "BL6, Ccr1-/- and Ccr2-/- mice were subcutaneously injected with LLC1.1 wt cells, the primary tumor was removed on day 14 and BL6 and Ccr2-/- mice were i.v. injected with fluorescently labeled Ccr2-/- enriched CD115+ monocytic cells." (PMID 39566333, 2025). "CD4+ central memory T cells (Panel2-C17) also exhibited elevated CCR2 and CCR7 expression, potentially facilitating tumor-directed migration." (PMID 41194936, 2025). "Preclinical studies in mouse models of hepatocellular and liver cancer demonstrate that CCR2 antagonists reduce TAM populations and increase infiltration of CD8+ T cells, further promoting anti-tumor immunity." (PMID 41019045, 2025). "In a Lewis lung cancer model, CCR2 knockout or the CCR2 inhibitor RS504393 reduced TAM recruitment, shifted TAMs to an M1 phenotype, and suppressed angiogenesis and tumor progression." (PMID 40079009, 2025). "In particular, the CCL2/CCR2 axis, the inhibition of the Ras/Raf/MAPK pathway, and the differential expression of miR-142, miR-146a, and miR-223 in tumor cells appear to play a critical role and have high clinical relevance." (PMID 40061903, 2025). "Clinically, therapeutic strategies targeting the tumor microenvironment (TME) such as CSF1R inhibition, CCR2/CCR5 blockade, and CD40 agonism show promise in preclinical and early-phase trials, especially when combined with immunotherapy." (PMID 40995363, 2025). "Therapeutic strategies targeting TAMs are rapidly evolving and include agents that block macrophage recruitment (e.g., CCR2 or CSF1R inhibitors), reprogram TAMs toward M1-like anti-tumor phenotypes, or deplete pro-tumoral populations." (PMID 40725175, 2025). "Muc16-directed CAR-T cells engineered to express CCR2, the cognate receptor to CCL2, demonstrate better in vitro and in vivo tumor-directed trafficking and improve survival in tumor-bearing mice." (PMID 41424784, 2025). "Initial candidates for overexpression have been the chemokine receptors CCR2 and CXCR2 (receptors for CCL2 and CXCL8/IL-8, respectively) for CAR and transgenic TCR T cells, as well as TILs, which revealed increased tumor infiltration in several models." (PMID 41181132, 2025). "In ACC, a key signaling axis involves tumor-derived CCL2 recruiting CCR2+ TAMs, which in turn secrete GDNF to drive tumor cell proliferation via the RET pathway." (PMID 41164198, 2025). "Once within the tumor, these BMDMs differentiate into CX3CR1+CCR2− TAMs and acquire an M2-like immunosuppressive phenotype, promoting immune evasion." (PMID 41002423, 2025). "Key chemokines involved in CD8+ T cell recruitment (CCR3, CXCL10, CXCL9) and their receptors (CCR2, CCR5, CXCR3) were consistently downregulated in FAM174B-high tumors, potentially limiting effector immune cell trafficking to the tumor microenvironment." (PMID 40959568, 2025). "For example, CAR-T cells engineered to express chemokine receptors such as CXCR1, CXCR2, or CCR2 demonstrate enhanced migration toward tumor sites that secrete corresponding chemokines, such as CXCL8 for CXCR1/2 and CCL2 for CCR2." (PMID 41584600, 2025). "In theory, CCL2 blockade can simultaneously inhibit the recruitment of immunosuppressive cells and enhance the infiltration of killer T cells to achieve tumor suppression, but the clinical benefit of targeting the CCL2/CCR2 axis is still pending." (PMID 41341593, 2025). "Since CCL2/CCR2 signaling is a central signaling pathway that promotes monocyte recruitment into the TME, CCR2 inhibitors eliminate TAMs and inhibit tumor proliferation." (PMID 41008931, 2025).
tumor (continued). "In a murine CRC model, the antihypertensive agent reserpine is shown to block lactate-induced HCAR1 signaling, suppress the recruitment of CCR2 + PMN-MDSCs, restore CD8+ T cell-mediated antitumor immunity, and enhance tumor sensitivity to anti-PD-1 therapy." (PMID 41152975, 2025). "MiVs, abundant in protein content from M1 macrophages, have demonstrated inherent tumor-targeting properties, partly due to C-C chemokine receptor type 2 (CCR2)-rich membranes, encouraging the homing of donor cells to tumor sites." (PMID 40485727, 2025). "As such, solid cancer - BMN crosstalk not only impacts hematopoiesis but also tumor vascularization and even angiogenesis as CCL2 gradients recruit CCR2+ inflammatory Mos, which produces VEGF to increase vascular permeability." (PMID 39148724, 2024). "MCP-1 binding to its receptor CCR2 activates monocytes and induces leukocyte infiltration, as well as T-cell proliferation; it acts also as a regulator in the polarization of Th0 cells toward a Th2 phenotype and, coupled with IL-4 signaling, it could contribute to tumor growth and metastasis." (PMID 38443899, 2024). "Examination of bone metastases in breast cancer models revealed a subset of macrophages originating from Ly6C+CCR2+ inflammatory monocytes characterized by increased expression of CD204 and IL4R, which have tumor-supportive functions." (PMID 39402303, 2024). "The CCL2/CCR2 axis is crucial for monocyte mobilization into the TME, and a myriad of preclinical mouse tumor models have proven this axis is both protumoral and targetable." (PMID 38786066, 2024). "In line with the T cell-inflamed TME, we detected a transient infiltration of inflammatory CCR2+ monocytes, Mono(ACT), pDC and DN DC on tumor-targeted therapy that was abrogated in resistant tumors." (PMID 38631706, 2024). "Moreover, inhibiting both AR and CCL2/CCR2 signaling could reduce tumor progression in vivo." (PMID 39286635, 2024). "Their migration into metastatic tumor colonies required signaling between CCL2 and CCR2, and their antitumor effects required CCL6-dependent recruitment of NK cells." (PMID 39545417, 2024). "PF-04136309, a specific CCR2 inhibitor, significantly reduces inflammatory TAM infiltration and inhibits tumor metastasis in preclinical PDAC models." (PMID 39286635, 2024). "Introducing CCR2 expression on CAR T cells enhanced trafficking, infiltration, and homing of CAR T cells at the tumor sites." (PMID 38819641, 2024). "Mechanistically, HDAC5 in tumor cells inhibits Socs3, a negative regulator of CCL2, resulting in a shift from neutrophils to CCR2-expressing macrophages." (PMID 38167055, 2024). "Results from our bioinformatic study revealed CCL2/CCR2 as one of the five pathways most upregulated within NK cells and HPV − tumor cells (vs. HPV + tumor cells)." (PMID 38468260, 2024). "Currently, synthetic inhibitors of CCL2, Bindarit(Bnd) and Carlumab(CNTO 888), as well as CCR2 antagonists RS-50439 and MLN1202, have been developed for targeted disruption of CCL2/CCR2 signaling to intervene in the progression of various tumor types." (PMID 38650924, 2024). "Research has demonstrated that blocking the CCL2/CCR2 axis with CCR2 antagonists, either on their own or in conjunction with other compounds, reduces the presence of MDSC in tumors and enhances tumor condition in preclinical mouse models." (PMID 38717677, 2024). "By interacting with CCR2, CCL2 facilitates cancer cell migration and recruits immunosuppressive cells to the tumor microenvironment, thereby promoting cancer development." (PMID 38533503, 2024). "Within the tumor tissues, there was a greater presence of CCL2 and CCR2 in the stroma compared to the cancer nests." (PMID 39308672, 2024). "Several studies revealed that the CCL2/CCR2 and CXCL17/CXCR8 axes are involved in recruiting monocytes into the site of inflammation and tumor." (PMID 38835055, 2024).
tumor (continued). "In Ccr2-/- collagen I tumors, P4HA1 and PLOD3 protein expression is notably reduced, underscoring the key role of TAMs in ECM dynamics and tumor progression." (PMID 39068459, 2024). "Following skin injury, however, perifollicular levels of BMP decline and keratinocyte-derived CCL2 initiate the chemotaxis and recruitment of both CX3CR1+CCR2+ and Ly6C+CCR2+ macrophages; these macrophages produce several cytokines including TGF-β." (PMID 38396697, 2024). "Our computational analysis suggests that HPV − tumor cells have a stronger reliance on IL6/IL6R and CCL2/CCR2 signaling within the tumor microenvironment (TME) to evade NK cell immune attack, in contrast to HPV + tumors." (PMID 38468260, 2024). "The CCL2/CCR2 signaling axis also recruits various immune cells to form an immunosuppressive TME in both the early and late stages of metastasis, which allows tumor cells to evade immune surveillance." (PMID 38468260, 2024). "We validated that EHF promotes the migration and infiltration of TAMs into tumors through the CCL2/CCR2 axis, which complements the function of GLI1 in tumor cells and provides a more comprehensive mechanism for EHF‐mediated cholangiocarcinogenesis." (PMID 38741887, 2024). "Another approach to recruiting T cells into tumor is to use constructs expressing a chemokine receptor, such as CCR2, CCR2b, CXCR3, CCR4, CCR7, CXCR2, or CXCR4, which can interact with the relevant tumor-derived chemokine." (PMID 38927974, 2024). "The study determined that the combination of anti-PD-1 immunosuppressant, CCR2/CCR5 antagonists and RT (3 × 8 Gy) was found to inhibit the infiltration of M2-type TAMs, Tregs and MDSCs, and this combination had better anti-tumor effects." (PMID 38434964, 2024). "While the mice model of HNSCC treated with radiotherapy, there showed an increase in the production of the chemotactic factor CCL2 in tumor cells, leading to the accumulation of CCR2-dependent TNF-α-producing monocytes/macrophages and CCR2+ Tregs." (PMID 38650924, 2024). "Treatment with either hippuric acid or a CCR2 antagonist inhibited MPE and tumor growth, with an even more pronounced effect observed when both treatments were combined." (PMID 39664577, 2024). "In brief, chemokine signaling is crucial for tumor angiogenesis (CXCR2 and CXCR4), immunosuppression (CXCR3 and CCR2), and tumor progression and metastasis (CCR5 and CXCR6)." (PMID 39456552, 2024). "CCL2 binding to CCR2 initiates downstream signaling pathways such as JAK/STAT and PI3K/AKT, which activate various transcription factors and genes that promote tumor cell growth and survival." (PMID 39201480, 2024). "Coculture experiments demonstrated that these stromal cell responses were mediated by tumor-derived CCL2 and CCR2-mediated suppression of the T-cell activating cytokine CD154 (CD40L)." (PMID 37208442, 2023). "In pancreatic cancer, TAM-derived C-X-C motif chemokine ligand 3 (CXCL3) targets CAFs’ C-X-C motif chemokine receptor 2 (CCR2) to mediate CAF-myofibroblasts (myCAF) transition, subsequent type III collagen generation and tumor metastasis." (PMID 36906534, 2023). "The TGF-β trap component of CSF1R/CCR2/TGF-β Ab can neutralize TGF-β, thereby enhancing the efficacy of CD8 T cells or NK cells and reducing tumor size in mice." (PMID 38076998, 2023). "For example, tumor secretion of TNF-α induces the chemokines CCL2 and CCL8 by TAMs which recruits additional CCR2+ monocytes to the TME." (PMID 37114134, 2023). "Depleting these mediators or receptors on respective immune cells (ie, CCR2 and CNTFR) can reignite antitumor immunity and constrain tumor growth, rendering these factors attractive therapeutic targets." (PMID 36708970, 2023). "The mRNA levels of CCR2, CCL2, VEGF, NF-κB, c-Myc, vimentin, and IL33 were determined in the CT26 cell line and then tumor tissues (after 21 days), by qRT-PCR." (PMID 37325423, 2023).
tumor (continued). "Kynurenine produced by glioblastoma cells can activate aryl hydrocarbon receptors and upregulate the expression of CCR2 and CD39 on macrophages, thereby increasing adenosine levels and suppressing tumor-specific T cell response." (PMID 37313405, 2023). "Double immunofluorescence microscopy showed that tumor-infiltrating CD11c+ cells were positive for CCR1 and CCR2 (receptors of CCL7) in the control group." (PMID 37046033, 2023). "In contrast, CD8+ TRM cells expressing only CXCR3 (population 14) and co-expressing CXCR3, CCR2, and CCR5 (population 2) were largely confined to the distal non-tumor area." (PMID 37448786, 2023). "The drug 747 is considered a selective CCR2 antagonist and has been shown to inhibit TAM recruitment and increase density of CD8+ tumor infiltrating lymphocytes as well as increase inflammatory cytokines such as IFN-γ in rodent mode." (PMID 37114134, 2023). "The results of the chemotaxis assays demonstrated that FAM171B overexpression enhanced the chemotaxis of macrophages towards tumor cells in the coculture system, while HNRNPU knockdown and CCR2 inhibition partially attenuated this effect." (PMID 37915048, 2023). "The present study also demonstrated that LPS injection after general anaesthetic exposure induced tumour volume reduction, high MPO and CCR2 expression, more neutrophil infiltration, and less M1 and pan macrophage infiltration." (PMID 35953652, 2023). "In mouse models, CCR2 genetic knockout mediated-MoMΦ selective depletion didn’t affect PDAC growth, indicating a dispensable role for them in tumor progression." (PMID 37771596, 2023). "MMPs together with VEGF-C, activates the CCL2/CCR2 signaling pathway and attracts circulating monocytes into the TME, thereby promoting tumor growth, expansion, and metastasis." (PMID 38033495, 2023). "Targeting both CCL2/CCR2 and CSF-1/CSF-1R axis is therefore relevant to a tumor that overexpresses M-CSF, CCL2 and other chemokines that bind to CCR2 such as CCL7." (PMID 38076998, 2023). "Similar to the tumor-bearing mice, GEM treatment induced accumulation of macrophages (CCR2+CD11b+F4/80+) and monocytes (CCR2+Ly6C+) in the lungs." (PMID 36976637, 2023). "targeted monocyte and macrophage tumor infiltration with CSF1R and CCR2 inhibitors in a PDAC mouse model." (PMID 37575220, 2023). "recently confirmed that microglial genes (CX3CR1, TMEM119, and P2RY12) were mainly expressed in the periphery, while activated macrophage genes (TNF, CCL2, LYZ, CCR2, CXCR4, and SIGLEC1) were predominantly detected within the core tumor regions." (PMID 37731483, 2023). "The CXCR4 and CCR2 expressed on UMSCs can interact with overexpressed SDF-1α and MCP-1 in GBM40–42, thus providing tumor-homing tropism." (PMID 36650171, 2023). "Nevertheless, it is safe to assume that CCR2+ monocytes recruited into the TME contribute to the immunosuppression of cytotoxic lymphocyte functions and thus promoting tumor progression in vivo." (PMID 37849753, 2023). "Kynurenine present in tumor-conditioned media activate AHR (aryl hydrocarbon receptor) in macrophages, resulting in increased expression of CCR2 as well as recruitment of TAM." (PMID 37598273, 2023). "Such chemokine signaling involved the receptors for CCL2 (CCR2), CCL5 (CCR5), and CXCL12 (CXCR4), which also enhanced STAT-3 activity and M2 polarization of macrophages and retention inside the tumor." (PMID 36902456, 2023). "Depleting fibroblastic STAT3 or CCL2, or murine CCR2 attenuated the FAP-induced MDSC infiltration and tumor-promoting effects in vivo." (PMID 36708970, 2023). "Chemokine axes such as C-C motif chemokine ligand 2 (CCL-2)/C-C motif chemokine receptor 2 (CCR2) and CCL-5/CCR5 can recruit monocytes/macrophages from the blood to the tumor region." (PMID 36902024, 2023). "Then, we analyzed the expression of CXCR2 and CCR2 on M-MDSCs and PMN-MDSCs, which were isolated from lung tissues of 4T1 tumor-bearing mice." (PMID 37268941, 2023).